RNU2-10P (RNA, U2 small nuclear 10, pseudogene)
Gene: Small nuclear RNA gene on chromosome 3 (62,118,300 to 62,118,510, reverse strand). Ensembl gene ENSG00000252184.
Homologues: Orthologues: chimpanzee U2 (99% identical), rabbit U2 (35% identical), rat U2 (28% identical). Paralogues in human: RNU2-8P (39% identical), RNU2-15P (38% identical), RNU2-58P (38% identical), RNU2-48P (38% identical), RNU2-33P (37% identical), RNU2-41P (36% identical), RNU2-12P (35% identical), RNU2-28P (35% identical), RNU2-55P (35% identical), RNU2-72P (35% identical), U2 (33% identical), RNU2-2 (33% identical), and 64 more.